SNORD22 (small nucleolar RNA, C/D box 22)
Synonyms: U22; RNU22
Gene: Small nucleolar RNA gene on chromosome 11 (62,852,910 to 62,853,035, reverse strand). Ensembl gene ENSG00000277194.
Gene Ontology:
Biological process: RNA processing
Cellular component: nucleolus
Homologues: Orthologues: chimpanzee SNORD22 (100% identical), macaque SNORD22 (98% identical), dog SNORD22 (90% identical), rat LOC120100233 (90% identical), mouse Snord22 (89% identical), dog SNORD22 (88% identical), dog SNORD22 (87% identical), rat Snord22 (87% identical), dog SNORD22 (85% identical), rat LOC120101999 (79% identical), macaque SNORD22 (75% identical), dog SNORD22 (71% identical), and 2 more. Paralogues in human: SNORD22 (61% identical).
Diseases named in the same sentence as SNORD22 in open-access papers:
SNORD22 is named in the same sentence as 1 disease in open-access papers, as found by Europe PMC text mining. Sharing a sentence is not in itself a finding about the gene and the disease. The quoted sentences say what the papers report.
infection (1 paper, 2022). The state of being infected such as from the introduction of a foreign agent such as serum, vaccine, antigenic substance or organism. "The silencing of SNORA/Ds encoded within RPS11 (SNORD35B), SNHG3 (SNORA73A, SNORA73B), and SNHG1 (SNORD22, SNORD25, SNORD26, SNORD27, SNORD28, SNORD29, SNORD30, SNORD31) inhibited infection with influenza A virus." (PMID 36430145, 2022).